BAMBI (BMP and activin membrane bound inhibitor)
Diseases named in the same sentence as BAMBI in open-access papers (continued):
Sharing a sentence is not in itself a finding about the gene and the disease.
cancer (continued). "In an effort to translate this finding to humans, we calculated the mRNA levels of BAMBI in biopsies from cancer patients (NCT03223155); patients received stereotactic body radiotherapy (SBRT) and ipilimumab plus nivolumab (ipi/nivo) immunotherapy." (PMID 38099498, 2023). "Our findings demonstrate that IR specifically reduces BAMBI expression in MDSCs in both human and murine cancers." (PMID 38099498, 2023). "The functional role of BAMBI needs to be further explored in other immune populations, especially in the setting of cancer." (PMID 38099498, 2023). "This study is the first study demonstrating the effect of CTGF/BAMBI axis on regulation of MM cell proliferation and thus adds to a growing body of literature identifying BAMBI as a potential treatment target for cancer therapy." (PMID 36109807, 2022). "Several studies have demonstrated that BAMBI is expressed in many human organs and is involved in organ fibrogenesis and cancer development." (PMID 27243216, 2016). "Therefore, we validated the expression of BAMBI in each cancer type using the University of ALabama at Birmingham CANcer data analysis portal (UALCAN)." (PMID 39684424, 2024). "In order to explore the importance of the BAMBI gene as a prognostic indicator, we analyzed the expression profiles of BAMBI, along with its contributions to pathological findings, metastasis characteristics, and prognosis in various human cancers." (PMID 39684424, 2024). "BAMBI mRNA levels did, however, not differ between EBV-positive and EBV-negative cancers, and the function of BAMBI in EBV-associated tumors needs further study." (PMID 36834884, 2023). "IR specifically reduces BAMBI expression in MDSCs in human and murine cancers." (PMID 38099498, 2023). "We suggest that CTGF controls cancer cell growth at least in part by regulating BAMBI expression, although the detailed molecular pathways remain unclear." (PMID 36109807, 2022). "In line with this study, 43 genes (including CLIP4) were downregulated in ovarian cancer tumor samples and reactivated after treatment with 5-Aza-2'-deoxycytidine (5-aza-dC); CLIP4, GULP1, BAMBI, NT5E, and TGFB2 showed a pattern of cancer-specific methylation." (PMID 33575272, 2020). "FGF2 and CHEK4 are up-regulated while the expression of CHEK1, WT1, MDM2, BARD1, BMP2, BAMBI, and SOD2, have been reported to be down-regulated in several cancer subtypes, including CRC." (PMID 31623294, 2019). "Most studies agree that BAMBI mRNA expression is elevated in cancer tissues compared to the respective non-tumorous tissues." (PMID 36834884, 2023). "The BAMBI (Vanhara and Souček, 2013), LCN2, F13A1, CDKN2A, SLIT2, and CLU were reported to individually play a role in cancer development and progression." (PMID 33585439, 2020).
infection (8 papers, 2010 to 2025). The state of being infected such as from the introduction of a foreign agent such as serum, vaccine, antigenic substance or organism. "Increased expression of BAMBI in COVID‐19 patients may indicate underlying susceptibility to viral invasion and infection." (PMID 40476695, 2025). "Both in vivo and acute in vitro NTHI infection were associated with marked upregulation of BAMBI." (PMID 20513241, 2010). "A recent study has demonstrated higher expression of the angiotensin-converting enzyme 2 (ACE2) and increased infection with SARS-CoV-2 upon BAMBI knock-down in Huh7 cells." (PMID 39457709, 2024). "We first examined mRNA and protein expression of BAMBI in cells by qPCR and western blot and confirmed successful infection of adenoviruses in AdBambi-infected and AdshBambi-infected cells." (PMID 27243216, 2016). "Regarding TGF-β expression we found a moderate increase, whereas a strong expression of BAMBI with 3-fold increase after in vitro infection of COPD lung tissue was demonstrated." (PMID 20513241, 2010). "Transcriptome arrays showed no significant changes of TGF-β receptors 1 and 2 and Smad-3 expression, whereas a strong expression of BAMBI with upregulation after in vitro infection of COPD lung tissue was demonstrated." (PMID 20513241, 2010). "In vitro infection revealed that NTHI induces a strong upregulation of BAMBI in the lung tissue on AM and AEC as well as on isolated AM and A549 cells." (PMID 20513241, 2010). "One of the genes strongly upregulated upon infection was the TGF-β-pseudoreceptor BMP and activin membrane-bound inhibitor (BAMBI)." (PMID 20513241, 2010). "Infection of HUVECs with the lentiviral expression vector, which also contains a GFP construct, resulted in a ∼80% expression of the construct for BAMBI, as judged by GFP fluorescence." (PMID 20886049, 2010). "COPD patients with NTHI infection showed increased expression of BAMBI in the lung tissues when compared to non-infected patients." (PMID 20513241, 2010). "In vivo NTHI-infected lung tissue of COPD patients showed also a stronger expression of BAMBI on AM and AEC compared to lung tissue without NTHI infection and control tissue." (PMID 20513241, 2010).
metabolic disease (2 papers, 2021 to 2023). A congenital disorder (due to inherited enzyme abnormality) or acquired (due to failure of a metabolically important organ) disorder resulting from an abnormal metabolic process. "BAMBI overexpression in adipose tissues may also prevent adiposity and metabolic diseases." (PMID 36834884, 2023).
heart diseases (1 paper, 2022). "BAMBI plays important roles in the progression of various heart diseases including AS." (PMID 35603423, 2022).
kidney disease (1 paper, 2010). "BAMBI can modulate TGFβ action, and TGFβ action is very cell-specific, including as the major modulator of progression of renal diseases." (PMID 20886049, 2010).
BAMBI also shares sentences with these, for which no sentence is quoted: aortic valve stenosis (1 paper); basal cell carcinoma (1); cardiac hypertrophy (1); cardiovascular disease (1); diffuse large B-cell lymphoma (1); endometrial cancer (1); glaucoma (1); Hypercholesterolemia (1); II type diabetes (1); inflammation (1); leukemia (1); lipid metabolism disorders (1); metabolic syndrome (1); metastatic carcinoma (1); Non-Alcoholic Fatty Liver Disease (1); paraganglioma (1); pheochromocytoma (1); proliferative retinopathy (1); pulmonary disease (1); Salmonella Infections (1); skin cancer (1); squamous cell carcinoma (1); steatosis (1); thrombosis (1); Ureteral obstruction (1); uterine corpus endometrial carcinoma (1).